HLA-E (major histocompatibility complex, class I, E)
Diseases named in the same sentence as HLA-E in open-access papers (continued):
Sharing a sentence is not in itself a finding about the gene and the disease.
infection (continued). "Expression of H2-T23 (Qa-1/HLA-E) and FOXP3 was induced in thymus and liver of C57BL/6 mice, which exhibited defective control of viral load, suggesting a higher susceptibility to YFV17D infection." (PMID 26457200, 2015). "Moreover, they confirm the strong Th2 profile of the response against these peptides in active infection, in concordance with the phenotype of the HLA-E restricted, peptide specific CD8+ T-cell clones." (PMID 25803478, 2015). "Thus, to test the functional significance of the miR-376a(e)-mediated control of HLA-E during infection we isolated NK cells from four HCMVneg and four HCMVpos donors." (PMID 24586166, 2014). "In contrast, HLA-E levels were initially increased in HCMV infected cells (GFPpos), probably because of the viral UL40 protein, but were then reduced as infection prolonged, probably due to the editing of miR-376a(e) which results in the down regulation of HLA-E." (PMID 24586166, 2014). "Nonetheless, evidence for a causal role of HLA-E in NK cell subset expansion during an ongoing infection is lacking." (PMID 24086127, 2013). "However, infection of endothelial cells led to shedding of HLA-E molecules, but in contrast, JEV infection of HFF cells resulted in only upregulation of HLA-E expression on the cell surface." (PMID 24236107, 2013). "In particular, HLA-E-restricted CD8+ T-cell recognition of peptides from pathogens may be an important mechanism of immune regulation during infections, as was first demonstrated for Mycobacterium tuberculosis." (PMID 23049954, 2012). "This may be due to different ligands for CD94-NKG2C induced by HCMV or different peptides being presented by HLA-E during infection that alter CD94-NKG2C activity." (PMID 21151939, 2010). "Moreover, these epitopes likely are also recognized during infection since live mycobacterium infected monocytes were lysed by HLA-E/peptide stimulated effector T cells." (PMID 20195504, 2010). "This review highlights the current gaps in understanding of T-cell recognition of HLA-E–presented peptides across infections and explores how advancing this gap could guide the development of future HLA-E–based vaccines and immunotherapies targeting microbial pathogens." (PMID 41440003, 2025). "This increase might be due to migration of HLA-E/Mtb T cells to the primary infection site." (PMID 39790998, 2024). "To ascertain if differences in receptor-ligand interactions could be responsible for the impaired capacity of the NK cells to kill the TCD32dim subset, we studied the expression of MICA/B, ULBP-1, CD155, and HLA-E on the surface of HIV-infected CD4+ T cells after ex vivo infection." (PMID 35616530, 2022). "However, although similarly activated early post-infection, low expression of PD-1 could be a feature of HLA-E restricted anti-HCMV T-cell responses." (PMID 29709038, 2018). "HLA-E allele did not affect pathogen infection or the production of de novo DSA." (PMID 27493971, 2016). "Finally, it was important to assess whether these HLA-E restricted Mtb specific T-cells were also present in the circulation of TB patients during active infection." (PMID 25803478, 2015). "Nevertheless, it is possible that more EBV peptides may bind to HLA-E during infection." (PMID 23049954, 2012). "Subsequent studies detected a specific HLA‐E‐restricted T‐cell response to an allogeneic HLA‐I leader peptide (VMAPRTLIL), presumably primed upon infection by an HCMV strain bearing that UL40 sequence." (PMID 40347012, 2025). "In contrast, natural infection induces robust activation, underscoring the differential immunogenicity of BCG versus natural exposure in shaping HLA-E-mediated immunity." (PMID 41440003, 2025). "Mtb challenge significantly increased frequencies of HLA-E–Mtb CD3+ T cells in the BAL of unvaccinated RMs, suggesting migration to the primary infection site." (PMID 39460296, 2024).
infection (continued). "One-fifth of upregulated DEPs in the AD retinas were related to immune responses, including HLA-DRB1, APOC1, S100A1, HLA-E, IBA1, and S100β, and involved lymphocyte and myelomonocyte activation in the presence of neuroinflammation and infection." (PMID 36773106, 2023). "In contrast, we found six proteins altered by infection with CoV-2(B), among which five were downregulated (i.e., STAT1, HLA-E, TPR, TRIM25, and TRIM28)." (PMID 36175400, 2022). "Cytomegalovirus (CMV) causes lifelong infection that probably results in lifetime expression of vaccine genes, and this may, in addition to unusual CD8 responses that recognize peptides associated with HLA-E and major histocompatibility complex (MHC) class II, explain the success of the vaccine." (PMID 31413132, 2019). "Using a set of 11 HLA-E/UL40 peptide tetramers we demonstrated the presence of HLA-EUL40 CD8 αβT cells in up to 32% of seropositive HCMV+ hosts that may represent up to 38% of total circulating CD8 T-cells at a time point suggesting a strong expansion post-infection." (PMID 29709038, 2018). "Due to the known higher surface expression of HLA‐E*01:03 molecules, it is postulated that they are more effective at presenting pathogen‐derived peptides to CD8+ T cells, thus improving their ability to clear infections." (PMID 40764252, 2025). "In contrast to the HLA-E, HLA-G mainly provides inhibitory signals to natural killer (NK) cells, facilitating immune escape in cytomegalovirus (CMV), Hepatitis B Virus (HBV), and Hepatitis C Virus (HCV) infections." (PMID 41440003, 2025). "Moreover, KLEPTOSE® CRYSMEB increased both HLA-E and GITRL, a mechanism that can probably serve to help the immune system boost immunosurveillance upon infection." (PMID 39273695, 2024). "More importantly, HLA-E-restricted CD8+ T cells were detected at higher frequency in people with chronic HBV, providing evidence for the naturally occurring presentation of this epitope during infection." (PMID 39578466, 2024). "UL40-specific HLA-E-restricted (HLA-EUL40) CD8 T cells are only emerging as key players in HCMV immunity, and only a small amount of data are available on their phenotype and functions during the course of infection." (PMID 36980230, 2023). "Our findings established that unconventional HLA-E-restricted UL40-reactive CD8 T cells were almost as frequent as the “immunodominant” conventional HLA-A2-restricted pp65- and IE1-specific CD8 T responses years or even decades post infection." (PMID 36980230, 2023). "One potential advantage of HLA-E sampling different cellular compartments is in the setting of infections where antigens are not abundant." (PMID 36430890, 2022). "Cell surface levels of the nonclassical HLA-E also increased on A549 cells over the infection time course." (PMID 32321802, 2020). "The dual functionality of HLA‐E, through its ability to inhibit NK cells and activate non‐classical CD8+ T cells, has made it an intriguing target of research for both understanding the immunology behind pathogen infection and improving vaccine design." (PMID 30968409, 2019). "Although UL40-specific HLA-E-restricted CD8 T-cells have been described in a few HCMV seropositive (HCMV+) individuals, only sparse data are available concerning their characteristics and post-infection occurrence." (PMID 29709038, 2018). "PBMCs from 5 HCMV+ patients with a primary infection or a reactivation (KTR #104, #105, #107, #108, #109) were sorted and then amplified in vitro to reach a purity>95% (defined by tetramer staining using the HLA-E/UL40 complexes employed for sorting)." (PMID 29709038, 2018). "Moreover, these HLA-E restricted CD8+ T-cells inhibited Mtb growth inside cells, an important property to contribute to resolution of the infection." (PMID 25803478, 2015). "Importantly, increased levels of HLA-E following transduction of HFF cells with the anti-miR-376a(e) sponge, were observed following infection with AD169, Merlin, CI and the TB40/E strain (quantified in 6e)." (PMID 24586166, 2014).
infection (continued). "By contrast to human fetal foreskin fibroblasts and fibroblastic cell lines, HCMV-infection resulted in decreased cell surface HLA-E molecules without affecting the total amount of proteins in decidual fibroblasts." (PMID 23592985, 2013). "Like MYXV, infection with vMyx-M153KO did not affect expression of other NK ligands including HLA–E, MICA/B, ULBP1–3, and PVR (not shown)." (PMID 23762498, 2013). "Western blot analyses of total amount of HLA-E molecules demonstrated that HCMV-infection did not affect total amount of HLA-E proteins in decidual fibroblasts while increased levels were observed in MRC-5 cells expression." (PMID 23592985, 2013). "Mtb-infection of A549 cells resulted in robust IFN-γ production by NC-restricted HLA-E and MR1-restricted T cells, in a manner that was dependent on the HLA-Ib molecules HLA-E and MR1, respectively." (PMID 20613858, 2010). "Here, we demonstrate that infection of human primary lung tissue with SARS-CoV-2 leads to increased HLA-E expression and show that processing of the peptide YLQPRTFLL from the spike protein is primarily responsible for the strong, dose-dependent increase of HLA-E." (PMID 38804979, 2024). "However, unlike MHC-Ia, HLA-E resides in various cellular compartments during homeostasis, infection, or differentiation and has multiple potential antigen presentation pathways." (PMID 36430890, 2022). "It is possible to speculate that individuals restricted by HLA-EG have high levels of the HLA-E molecule with great affinity for viral antigens, which may increase NK cell and CD8+ T cell lysis of HIV-infected cells and subsequent protection from infection." (PMID 28769934, 2017). "Regardless of the peptide source, it is tempting to speculate that alterations in the HLA-E ligandome surveyed by the NKG2C receptor contribute differentially to the accumulation, differentiation and effector functions of adaptive NKG2C+ NK cells during infection." (PMID 32132995, 2020). "By contrast, reporter activation was undetectable upon interaction of Jurkat-NKG2C+ cells with HFFF or MRC5 fibroblasts following infection with common HCMV laboratory strains (i.e., AD169, Towne), regardless of their ability to preserve surface HLA-E expression in infected cells." (PMID 29114247, 2017).
infectious disease (11 papers, 2015 to 2025). A disorder directly resulting from the presence and activity of a microbial, viral, or parasitic agent in humans. "In the context of infectious diseases, HLA-E expression has been linked to activation of NK cells with antiviral capacity." (PMID 36466823, 2022). "HLA-E has been proven to present epitopes to interact with αβTCR on CD8+ T cells in several infectious diseases." (PMID 38257752, 2023). "NK cells could participate in the pathogenesis process of virus infectious diseases through the inhibitory receptor CD94/NKG2A interacting with HLA-E/virus-derived peptide complex." (PMID 40680069, 2025). "Qa-1, the murine equivalent of human HLA-E, is functionally important in mouse models of (intracellular) infectious diseases, underlining the functional contribution of non-classical class Ib restricted CD8+ T-cells to host defense." (PMID 25803478, 2015). "Finally, and perhaps of greatest importance, there is the question of whether MR1- or HLA-E-specific vaccination strategies can be developed for human infectious diseases." (PMID 36430890, 2022). "Previous studies established the emergence of HLA-E-restricted CD8 T cell subsets in autoimmune and infectious diseases." (PMID 35008688, 2021). "Recently, the studies have shown that the interaction of human leukocyte antigen E (HLA-E) and natural-killer group 2, member A (NKG2A) inhibitory receptors could regulate the functions of NK cells, participating the pathogenesis process of virus infectious diseases." (PMID 40680069, 2025). "Additionally, HLA-E-restricted CD8+ T cells can be expanded in vitro and could serve as a subset of MHC-unrestricted T cells with great potential for adoptive cell therapy in infectious diseases." (PMID 38106407, 2023).
bacterial infections (7 papers, 2016 to 2025). "It was also found that the presence of HLA‐E*01:03 in the donor's genotype (HLA‐E*01:01, 01:03, or HLA‐E*01:03, 01:03) reduced the risk of severe bacterial infection post‐transplant compared to HLA‐E*01:01, 01:01 donors." (PMID 40764252, 2025). "There are several studies concerning associations of HLA-E alleles with bacterial infections." (PMID 31690066, 2019). "This review examines the expanding role of HLA-E-restricted T cells in viral and bacterial infections and their capacity to recognize diverse microbial peptides and enhance immune response when classical HLA pathways are impaired." (PMID 41440003, 2025). "HLA-E plays a pivotal role in coordinating innate and adaptive immune responses during bacterial infections by functioning both as a ligand for NK-cell receptors and as a non-classical antigen-presenting molecule for CD8+ T cells." (PMID 41440003, 2025). "Under conditions such as viral or bacterial infections, HLA-E can present pathogen-derived peptides to unconventional, HLA-E-restricted CD8+ T cells via their αβ T cell receptor." (PMID 41283666, 2025). "None of the HLA-E alleles were significantly associated with the different clinical variables, such as bacterial infection at M1 or M3 and DSA detection at M1 and M3." (PMID 27493971, 2016). "None of the HLA-E alleles were associated with a higher risk of bacterial infection at M1 and M3." (PMID 27493971, 2016).
hematological malignancies (5 papers, 2016 to 2024). "HLA‐E overexpression has been detected in various solid and hematological malignancies." (PMID 39623605, 2024). "HLA-E is frequently upregulated on cells from many hematological malignancies or solid cancers." (PMID 29023417, 2017). "Monalizumab has already shown efficacy to strengthen NK cell responses against HLA-E overexpressing tumor cells in preclinical models, prompting its usage in various ongoing clinical trials including solid cancers and hematological malignancies (Clinical trial.gov)." (PMID 29023417, 2017). "Recently, it has been suggested that latent CMV infection-mediated increase in the proportion of NKG2C+ NK cells may prime NK cell cytotoxicity and could be beneficial in preventing the progression and development of hematologic malignancies characterized by high HLA-E expression." (PMID 27493971, 2016).
neurodegenerative disease (2 papers, 2022 to 2025). A disorder of the central nervous system characterized by gradual and progressive loss of neural tissue and neurologic function. "Interestingly, we found a greater number of BST2, HLA-E, PD-L1, and PDPN positive GFAP+ astrocytes in AD post-mortem brains compared to brains from non-symptomatic individuals, warranting further investigations on the roles that these markers play in neurodegenerative disease." (PMID 35592112, 2022).
hematological cancers (1 paper, 2023). "The importance of this inhibitory pathway is reflected by the established association of HLA‐E expression with poor prognosis in series of solid and hematological cancers." (PMID 37782273, 2023).
neurological diseases (1 paper, 2025). "In this review, we summarize and discuss current knowledge of the role of HLA-E in herpesvirus-associated neurological diseases." (PMID 41283666, 2025). "In this review, we therefore aim to summarize and discuss current knowledge and future directions regarding the role of HLA-E in herpesvirus-associated neurological diseases, highlighting its potential as both a biomarker and a therapeutic target." (PMID 41283666, 2025). "Thus, understanding the context-dependent effects of HLA-E may aid in predicting individual risk for neurological disease in HHV-infected individuals and in guiding the design of targeted immunotherapies that protect neural tissue while appropriately modulating neuroinflammation." (PMID 41283666, 2025).
psychiatric disorder (1 paper, 2023). A disorder characterized by behavioral and/or psychological abnormalities, often accompanied by physical symptoms. "Among genes mapped to loci shared between AN and psychiatric disorders, several immune-related genes were implicated, including the C4A, C4B, NCAM1, HLA-B, HLA-C, and HLA-E genes." (PMID 37658054, 2023).
HLA-E also shares sentences with these, for which no sentence is quoted: multiple myeloma (13 papers); lupus (7); experimental autoimmune encephalomyelitis (6); osteosarcoma (5); atherosclerosis (2); chronic hepatitis B (2); colitis (2); diabetes (2); erythroleukemia (2); kidney cancer (2); prostate carcinoma (2); rectal cancer (2); thyroid cancer (2); viral disease (2); adenocarcinoma (1); AIDS (1); Alzheimer disease (1); anaplastic oligodendroglioma (1); ankylosing spondylitis (1); astrocytoma (1); Atrophy (1); autoimmune thyroid disease (1); autoimmune type 1 diabetes (1); B-cell acute lymphocytic leukemia (1); bipolar disorder (1); breast adenocarcinoma (1); cervical intraepithelial neoplasia (1); Chronic myelogenous leukemia (1); colorectal adenocarcinoma (1); deafness (1).
A further 27 diseases each share a sentence with HLA-E in 1 paper.